IL6 (interleukin 6)
Diseases named in the same sentence as IL6 in open-access papers (continued):
Sharing a sentence is not in itself a finding about the gene and the disease.
prostate carcinoma (continued). "Cytokines produced during this process, such as interleukin-6 (IL-6), tumor necrosis factor-alpha (TNF-α), and interleukin-8 (IL-8), along with chemokines like CCL2 and CCL12, are thought to be pivotal in bridging the progression to prostate cancer." (PMID 39355131, 2024). "Likewise, specific cytokines such as IL-6, TNF-a, IL-15, and IL-1 have been postulated to promote or inhibit cancer cachexia and prostate cancer by affecting several aspects of lipid metabolism." (PMID 38916917, 2024). "IL-6 mediates AR-independent activation in prostate cancer cells in the absence of androgens, and MAPK involvement is necessary." (PMID 38553750, 2024). "We observed that CA could block the IL-6 mediated STAT-3 signaling pathway, leading to apoptosis in prostate cancer cells." (PMID 39574470, 2024). "Researchers have found that alternol induces ICD in prostate cancer cell lines by increasing DAMPs levels (HMGB1, ATP release, and CRT translocation; pro-inflammatory cytokines such as IL-1 A, IL-1B, IL-8, and IL-6) and stimulating the immune response against tumors in prostate cancer cells." (PMID 37705051, 2023). "IL-6, via the IL-6R/JAK2/STAT3 signaling pathway, stimulated polarization of M2 macrophages, which accumulate in prostate tumor tissue and contribute to the proliferation of prostate cancer cells." (PMID 37125086, 2023). "In contrast, race-specific differences were observed for significantly higher serum levels of CXCL2 (p < 0.0001), CXCL5 (p = 0.016), and IL-6 (p = 0.004), and lower levels of CCL23 (p < 0.0001) and CCL27 (p = 0.016) in AA prostate cancer patients (n = 14) compared to CA (n = 14)." (PMID 37698493, 2023). "BPH tissues and prostate cancer cells express toll-like receptor 4 (TLR4) and are characterized by increased immune-mediated inflammatory processes and secretion of cytokines, such as IL-1β, IL-6, IL-8, TNF-α, and COX-2." (PMID 36771389, 2023). "In addition, in prostate cancer, EHF binds to the EBS in the promoter region of IL-6 and represses its transcription, resulting in STAT3 inactivation." (PMID 37958443, 2023). "For prostate cancer, missing data for ADT were 1.5% and 16.9% for both IL6 and TNFα." (PMID 36658635, 2023). "The level of IL-6 in BPH-1 cells infected with T. vaginalis is increased, and IL-6 is considered to be a factor promoting the development of benign prostatic hyperplasia and prostate cancer." (PMID 36864428, 2023). "In prostate cancer, EGR1 could upregulate angiogenic and osteoclastogenic factors, including PDGFA, IL6, IL8, etc. and thus promote cancer metastasis." (PMID 36932397, 2023). "The comparison of prostate cancer cell lines LnCaP, DU145 and PC3 sensitivity for selective conjugates 2, 4, 5 and 8 based on the results from cytotoxicity tests (MTT and LDH), apoptosis assay and IL-6 release inhibition." (PMID 35053570, 2022). "IL-6 plays a key role in prostate cancer but no data on ciliary neurotrophic factor (CNTF), a member of interleukin-6 cytokine family, are known." (PMID 36497399, 2022). "Our study found that cell models of advanced prostate cancer demonstrated constitutive expression of STAT-3, and also exhibited characteristics such as a high secretion of growth factors, such as VEGF and cytokines, such as IL-6 and CXCL8." (PMID 35465350, 2022). "IL-6-induced Glut5 expression promotes OSCC and prostate cancer cell growth." (PMID 35813468, 2022). "The goal of research was to investigate the possible relations between serum concentrations of IL-6 and TGF-β1, individual and clinical characteristics, and adverse effects of radiotherapy in patients with prostate cancer: acute and late genitourinary and gastrointestinal toxicity, and fatigue." (PMID 36368974, 2022).
prostate carcinoma (continued). "In present study, we utilized the TAMs/cancer cells co-culture system and proved that QL serum re-programmed the TAMs to M2 phenotype by targeting IL-6/STAT3 signaling pathway, resulting in restoring the sensitivity of paclitaxel-resistant prostate cancer cells to paclitaxel." (PMID 35193986, 2022). "Thus, treatment by the simultaneous inhibition of NF-κB and IL-6/STAT3 signaling is a possible therapeutic strategy to improve the response to chemotherapy and radiation in prostate cancer." (PMID 36010693, 2022). "Taken together, the results of our study demonstrate that circulating levels of IL-6 and TGF-β1 might influence the severity of acute GU radiotoxicity and fatigue in patients with prostate cancer treated with radiotherapy." (PMID 36368974, 2022). "Besides that, it has been noticed that IL-6 and transforming growth factor beta (TGF-β) gene expression levels change in PBMC in prostate cancer patients receiving RT38." (PMID 35525840, 2022). "Our results suggest that serum levels of IL-6 and TGF-β1 might influence the severity of acute genitourinary radiotoxicity and fatigue in patients with prostate cancer." (PMID 36368974, 2022). "We provide evidence of immunomodulatory intervention of MGF-AuNPs in prostate cancers through observations of enhanced levels of anti-tumor cytokines (IL-12 and TNF-α) with concomitant reductions in the levels of pro-tumor cytokines (IL-10 and IL-6)." (PMID 34408231, 2021). "PL was found to significantly inhibit the activation of NF-κB and modulate the expressions of NF-κB mediated proteins such as IL-6, IL-8, MMP-9, and intercellular adhesion molecule 1 (ICAM-1), thereby suppressing the metastatic potential of the prostate cancer cells." (PMID 36046754, 2021). "Interestingly, interleukin-6 (IL-6)-mediated STAT3 activation has been found to up-regulate PTTG1, thus leading to the malignant behaviors of prostate cancer cells." (PMID 34025420, 2021). "Interestingly, another pro-inflammatory marker, Il-6, was found to significantly increase the expression of CHGA in prostate cancer cells." (PMID 34620125, 2021). "Interestingly, the induction of EMP and invasiveness by IL-6/STAT3 has been shown to be mediated by Fra-1 expression in CRC and by PTTG1 in prostate cancer." (PMID 34361105, 2021). "In parallel, IL-6 acts on BMP-6 secreting malignant cells and enhances the expression of the androgen receptor, a major determinant of tumor growth and treatment response in prostate cancer." (PMID 33842333, 2021). "The inhibition of NF-κB kinase subunit alpha (IKKα) activity blocks the interleukin 6 (IL-6)/STAT-3 signalling pathway leading to a decrease in proliferation, migration, and invasion by inducing apoptosis of prostate cancer cells and inhibits tumour formation in a xenograft mouse model." (PMID 33806258, 2021). "Previous studies indicated that IL-6 and CXCL5 could induce androgen-independent prostate cancer progression." (PMID 33802402, 2021). "At this stage, there is no consensus regarding use of clinical anti-IL-6 therapy in patients with prostate cancer." (PMID 34204596, 2021). "A Phase 2 trial (NCT00433446) examining siltuximab (CNTO328), an anti-IL6 antibody, showed siltuximab did not have clinical benefit for patients with advanced prostate cancer." (PMID 34760886, 2021). "IL-6 and IL-6R were found in benign prostatic epithelium, but there was over-expression of both in adjacent pre-malignant high-grade prostatic intraepithelial neoplasm (HGPIN) lesions as well as in the malignant prostate tumor tissues." (PMID 33920379, 2021). "In prostate cancer, silencing Hsp27 can decrease IL-6-dependent STAT3 phosphorylation, nuclear translocation, and STAT3 targeting of the Twist promoter, indicating that Hsp27 is required for IL-6-mediated EMT via regulation of STAT3/Twist signaling." (PMID 32315283, 2020).
prostate carcinoma (continued). "For the supernatants of plasma-treated vs. control prostate cancer cells alone (not added to myeloid cells), a significant decrease was found for IL6 and VEGF." (PMID 32316245, 2020). "The exosomes that are secreted under hypoxia enhance the invasiveness and stemness of prostate cancer cells by targeting adherent junction molecules and increased level of diverse signaling molecules (TGF-β2, TNFlα, IL-6, TSG101, Akt, ILK1, MMP, and β-catenin)." (PMID 33076397, 2020). "Indeed, prostate cancer cells release high concentrations of TGF-β and IL-6 inside the TME, which play a mandatory role in the activation of resident fibroblasts into CAFs." (PMID 31991773, 2020). "In this study there is a negative correlation between the level of IL-6 gene expression and the percentage of Tregs in PB in patients with prostate cancer which is the most prominent after last fraction of radiotherapy." (PMID 33149212, 2020). "Also, inhibition of IL-6-JAK/STAT3 signalling result in the enhancement of NK cell-mediated cytotoxicity via alteration of PD-L1/NKG2D ligand levels, in castration-resistant prostate cancer cells." (PMID 33569050, 2020). "But experimental therapies against IL-6 and the clinical trials on patients with late-stage prostate cancer has not been yet reported." (PMID 35582225, 2020). "IL-6 acts through the Janus kinase (JAK)-signal transducer and activator of transcription (STAT) pathway which has been approached as anti-STAT3 therapeutics in several human cancers including prostate cancer." (PMID 35582225, 2020). "Prostate cancer cells express chemokine and chemokine receptors, as well as endogenously produced chemokines and cytokines such as MCP-1, TNF-α, IL-1β, IL-6, and IL-8, some of which are secreted at a higher level in PC-3 cells (mCRPC cell line) than in LNCaP cells (mCSPC cell line)." (PMID 33050597, 2020). "Moreover, IL-6/STAT3-induced DNMT1 enhances the metastatic potential and reduces radiosensitization in AR-prostate cancer and accumulates myeloid-derived suppressor cells, all of which are responsible for the accelerated tumor growth." (PMID 31952344, 2020). "Some studies showed that IL-6 acts as a contributing factor of autophagy in cancers, suggesting that the IL-6/p-STAT3 pathway is a positive regulator of autophagy in pancreatic cancer and in prostate cancer." (PMID 33066678, 2020). "Treatment of the AT1 cells with interleukin-6, a cytokine known to be involved in the pathogenesis of prostate cancer, did not affect the expression of the components of the NAE/MAG system studied." (PMID 32286386, 2020). "In prostate cancer p38 MAPK activation has been reported via TNFα and IL6." (PMID 30975102, 2019). "Accordingly, the modulation of Akt signaling in the gene expressions of NDRG1 and IL-6 may account for the functions of MIEN1 in cell proliferation, invasion, and tumorigenesis in prostate carcinoma cells." (PMID 31581708, 2019). "IL-6 expression in prostate tissues was increased in HFD-fed mice, as were the amounts of phosphorylated signal transducer and activator of transcription 3 (STAT3) in prostate cancer cells." (PMID 30736371, 2019). "Moreover, other studies have demonstrated that IL-6 induces NF-ĸB signals in human intestine epithelial (Caco2-BEE) cells and prostate carcinoma cells." (PMID 31581708, 2019). "This condition could constitute the breeding ground for the evolution of prostate cancer towards a more aggressive form (G9), involving a change in SHMT2 and PKM2 status through the IL-6/JAK2/STAT3 pathway." (PMID 31500219, 2019).
prostate carcinoma (continued). "A low-grade chronic inflammation caused by prostatic C. acnes infection, including induced secretion of IL6 and CXCL8, may thus over time contribute to prostate cancer development." (PMID 30473726, 2018). "Interleukin-6 (IL-6) which is known to augment cancer cell proliferation is directly regulated by AIRE at the genomic level and rescues the drug-induced cell death in PC3 prostate cancer cells." (PMID 29795364, 2018). "Cytokines such as IL-6 and RANKL have pleiotropic actions on prostate cancer cells." (PMID 28292326, 2017). "The reasons for these differences have not yet been clarified, and it appeared that IL-6 inhibited the growth of only LNCaP cells but not other prostate cancer cell lines." (PMID 28292326, 2017). "Immunomodulatory effect of the honey varieties was tested in prostate cancer cells PC-3 and PBMC (peripheral blood mononuclear cells) by measuring the IL-6 (interleukin 6) and NO (nitric oxide) levels in cell culture supernatant after incubation with the honey varieties." (PMID 28356100, 2017). "IL-6 acts through the Janus kinase (JAK)–signal transducer and activator of transcription (STAT) pathway and anti-STAT3 approaches have been proposed in several human cancers, including prostate cancer." (PMID 29214142, 2017). "We have also reported that prostate cancer cell lines lacking androgen receptor expression exhibit high constitutive IKKε expression and IL-6 secretion." (PMID 27577074, 2017). "For example, AR can be activated in the absence of androgens by interleukin-6 (IL-6) in human prostate cancer cells." (PMID 27741511, 2017). "Conclusions from recent clinical studies propose that serum IL-6 can be a negative prognostic biomarker for prostate cancer." (PMID 28077171, 2017). "Experimental therapies against IL-6 have been established; however, clinical trials were performed in patients with late stage prostate cancer and were not successful." (PMID 29214142, 2017). "Indeed, expression of multiple cytokine receptors including IL-6 and TNF-α is increased in prostate cancer in comparison to control tissue, and rises with Gleason grade." (PMID 26376613, 2015). "Meanwhile, a novel mechanism that IL-6 promoted prostate cancer metastases through a soluble IL-6 receptor (sIL-6R) without activation of STAT1, STAT3 or MAPK was also documented." (PMID 26528698, 2015). "In this study, we determined whether IL-6 regulates the expression of the PDCD4 gene and defined the role of miR-21 in this process in the prostate cancer cell lines LNCaP and PC-3." (PMID 26252635, 2015). "Previously, we have proposed our hypothesis that glucosamine could inhibit the N-glycosylation of IL-6 receptor in human prostate carcinoma DU145 cells, thereby reducing the activity of the IL-6/JAK/STAT3 signaling pathway." (PMID 24932134, 2014). "A data driven, multivariate approach, was used in this study to predict prostate cancer cell survival based on the phosphorylation levels of key proteins in PC3, LNCaP, and MDA-PCa-2b cell lines in response to EGF, IGF1, IL6, TNFα, dihydrotestosterone, and docetaxel treatment." (PMID 24885093, 2014). "IL-6 can convert non-ALDHhigh cells to ALDHhigh cells in prostate cancer cell line as well as from cells derived from human prostate tumors, the conversion mediated by IL-6 was abrogated in the presence of STAT3 inhibitor or upon STAT3 knockdown." (PMID 25261365, 2014). "The inflammatory cytokine IL-6 contributes to the growth and progression of various malignancies, such as HNSCC, prostate cancer and gastrointestinal cancer, and acts as an autocrine growth factor and an anti-apoptotic factor for various stimuli, including anticancer agents." (PMID 23561329, 2013).
prostate carcinoma (continued). "Interleukin-6 (IL-6) and CRP were reported to be elevated in prostate cancer patients and IL-6 may potentially be involved in the development or progression of prostate cancer." (PMID 22110984, 2011). "The involvement of IL6 and the JAK-STAT pathway in advanced prostate cancer is well known." (PMID 18492237, 2008). "In this study, we have measured serial levels of serum IL-6 and TNF-α in prostate cancer patients." (PMID 15150588, 2004). "In conclusion, these results suggest that IL-6 and TNF-α correlate with the extent of disease in patients with prostate cancer and may be monitored in conjunction with other disease markers." (PMID 15150588, 2004). "Both IL-6 and TNF-α were detectable in all control subjects and prostate cancer patients." (PMID 15150588, 2004). "IL-6 signalling is mediated through the Janus kinase (JAK), signal transducer, activator of transcription 3 (STAT3) and mitogen-activated protein kinase (MAPK), which induces AR-mediated gene activation in prostate cancer." (PMID 15150588, 2004). "Notably, PC3 cells, the more aggressive prostate cancer model, retained an expression profile consistent with their malignant phenotype, characterized by BCL-2 overexpression, PTEN downregulation, and increased expression of the inflammation-related gene IL-6." (PMID 41465187, 2025). "Beyond its pro-tumorigenic roles, IL-6 promotes angiogenesis by the VEGF signal pathway, thereby weakening the effectiveness of ICIs in many types of cancers, including gastrointestinal cancers, prostate cancer, oral squamous cell carcinoma, and hepatocellular carcinoma." (PMID 40519900, 2025). "Moreover, serum containing overexpressed ANXA2 showed higher levels of IL-6; the siRNA-mediated inhibition of ANXA2 expression in prostate cancer cells reduced IL-6 secretion, while the restoration of ANXA2 expression by transfection of the ANXA2 gene normalized IL-6 secretion." (PMID 39057791, 2024). "In previous studies, the overexpression of RTN4 in prostate cancer cells was shown to block the cell cycle in the G2/M phase and to induce cell senescence and the expression of inflammatory cytokines, such as CHOP, IL-6, and tumor necrosis factor (TNF)-α, in a muscle cell line (C2C12)." (PMID 36768745, 2023). "Prostate tumor cells produce large amounts of IL-6 and its receptor, IL-6R (gp80), and IL-6 functions as a paracrine growth factor for the human LNCaP androgen-sensitive prostate cancer cells and an autocrine growth factor for the human DU145 and PC3 androgen-insensitive prostate cancer cells." (PMID 36034203, 2022). "Indeed, CAF-derived IL-6 can induce VEGF secretion in established prostate cancer cells via PI3K/AKT signaling, and is independent of AR activation." (PMID 36671452, 2022). "Combining clinical parameters, patient’s individual characteristics, and circulating cytokine levels, especially IL-6 and TGF-β1, in prediction models might be useful for the prediction of adverse normal tissue reactions to radiotherapy in patients with prostate cancer." (PMID 36368974, 2022). "Bone marrow stromal cells were found to up-regulate G6PD expression via interleukin-6 (IL-6) secretion, and targeting G6PD either pharmacologically or genetically could inhibit prostate cancer proliferation, migration, mesenchymal phenotype, and sensitivity to chemotherapy." (PMID 35213227, 2022). "A neutralizing antibody to IL-6 was found to significantly reduce G6PD expression and STAT3 phosphorylation in prostate cancer cells treated with HS5 CM, demonstrating that bone marrow stromal cell–derived IL-6 can drive up-regulation of G6PD in prostate cancer cells." (PMID 35213227, 2022). "The activation of MALT1 on the expressions and secretions of IL-6 and CXCL5 was blocked under the treatment of MI-2 or CAPE, suggesting that upregulation of MALT1 on the IL-6 and CXCL5 expressions may rely on the MALT1/NF-κB pathway in prostate carcinoma cells." (PMID 33802402, 2021).